DNAI3 (dynein axonemal intermediate chain 3)
Description:
Via its association with the multisubunit axonemal dynein complex, is potentially involved in the regulation of cilia function (By similarity). May play a role in osteogenesis of dental tissue-derived mesenchymal stem cells (By similarity).
Synonyms: WDR63; DIC3; FLJ30067; NYD-SP29
Tractability: Small molecule: a structure with a bound ligand is known.
Gene: Protein-coding gene on chromosome 1 (84,999,147 to 85,133,138, forward strand). Ensembl gene ENSG00000162643.
Subcellular location: Cytoplasm
Subcellular location (Human Protein Atlas): Connecting piece; Calyx; Mid piece; Perinuclear theca
Gene Ontology:
Molecular function: Arp2/3 complex binding; protein binding; dynein heavy chain binding; dynein light chain binding
Biological process: negative regulation of Arp2/3 complex-mediated actin nucleation; negative regulation of cell migration; cilium movement involved in cell motility; inner dynein arm assembly; positive regulation of osteoblast differentiation
Cellular component: cytoplasm; axonemal dynein complex; inner dynein arm
Genetic constraint (gnomAD): Loss-of-function variants: 73 observed, 100.86 expected, observed/expected ratio (o/e) 0.72, 90% interval 0.6 to 0.88. The upper end of that interval is the gene's LOEUF score, 0.88, which puts it in group 3 of 6, group 1 being the genes least tolerant of losing a copy. Missense variants: 927 observed, 1,036.5 expected, observed/expected ratio (o/e) 0.89, 90% interval 0.85 to 0.94. Synonymous variants: 292 observed, 335.41 expected, observed/expected ratio (o/e) 0.87, 90% interval 0.79 to 0.96.
Homologues: Orthologues: macaque DNAI3 (96% identical), chimpanzee DNAI3 (95% identical), rabbit DNAI3 (87% identical), dog DNAI3 (86% identical), pig DNAI3 (84% identical), guinea pig DNAI3 (82% identical), mouse Dnai3 (81% identical), rat Dnai3 (78% identical), tropical clawed frog dnai3 (57% identical), zebrafish DNAI3 (40% identical). Paralogues in human: DNAI2 (14% identical), DNAI4 (14% identical), DYNC1I2 (13% identical), DYNC1I1 (13% identical), DNAI1 (12% identical), DYNC2I1 (12% identical), DYNC2I2 (11% identical).
Diseases named in the same sentence as DNAI3 in open-access papers:
DNAI3 is named in the same sentence as 7 diseases in open-access papers, as found by Europe PMC text mining. Sharing a sentence is not in itself a finding about the gene and the disease.
DNAI3 shares sentences with these, for which no sentence is quoted: Azoospermia (2 papers); cancer (2); Infertility (2); lung carcinoma (2); male infertility (1); primary ciliary dyskinesia (1); tumor (1).